BAP1 (BRCA1 associated deubiquitinase 1)
Diseases named in the same sentence as BAP1 in open-access papers (continued):
Sharing a sentence is not in itself a finding about the gene and the disease.
tumor (continued). "OMM2.3, originating from a metastasis and harbouring the BAP1 mutation, showed increased onset of migrating tumour cells in zebrafish, compared to its primary tumour counterpart, MEL270." (PMID 34149931, 2021). "BAP1, a tumour suppressor frequently mutated in human cancers, is ubiquitously expressed and inactivation or deletion of this gene results in metastasis." (PMID 34170818, 2021). "BAP1 is a nuclear ubiquitin hydrolase, which functions as a tumour suppressor, and is encoded by the BAP1 gene." (PMID 34209209, 2021). "BAP1 encodes a deubiquinating enzyme (nuclear ubiquitin carboxy-terminal hydrolase) and is a known tumor suppressor gene." (PMID 34771666, 2021). "Niraparib is being explored in patients with Trial (NCT03207347) in BAP1 and other DNA damage repair-deficient neoplasms, including MPM." (PMID 34067960, 2021). "BAP1 is a multifunctional tumor suppressor, and BAP1 mutations in UM are associated with activation of regulatory immune cells and an imunosuppressive tumor microenvironment." (PMID 34298857, 2021). "Further, upregulation of the cystine transporter xCT (encoded by SLC7A11) in BhomoKA compared to KA neoplasms suggests a potential role for ferroptosis deregulation in the tumor-promoting phenotype induced by BAP1 loss." (PMID 34830866, 2021). "MPM, by contrast, has been characterized primarily by tumor suppressor loss, and in the case of BAP1, by mutations in tumor cells that are highly variable among tumors and thus less practical to detect using a targeted sequencing approach." (PMID 32944962, 2021). "For instance, BAP1 (BRCA1-associated protein 1) is a tumour suppressor that regulates cell cycles, cell differentiation and DNA damage response pathways." (PMID 34572747, 2021). "The second inactivating somatic mutation in BAP1 in Patient A’s tumor occurred through an 11-base pair frameshift mutation NM_004656.4:c.1092_1102del (p.His364GlnfsTer30) consistent with a loss of function BAP1 variant." (PMID 34504799, 2021). "Of the patients who had a miliary metastasis pattern (n = 24), 17 had a primary BAP1-mutated tumor and two had a primary SF3B1-mutated tumor." (PMID 34771480, 2021). "Recent molecular studies of human tumor samples have demonstrated that somatic mutations in BAP1 and KRAS are among the most frequent mutations present in ICC." (PMID 34830866, 2021). "The timing of micrometastatic seeding has been estimated as 4.2 years after tumor initiation, which aligns with the calculated timing of the BAP1 mutation." (PMID 33903674, 2021). "BRCA1-associated protein 1 (BAP1) is a tumor suppressor that regulates multiple processes, such as cell cycle control, programmed cell death, DNA damage repair, chromatin modification, and the immune response." (PMID 34733850, 2021). "Using the same doubling time for the cell population with loss of BAP1 expression, the first tumor cell with lost BAP1 expression appeared an average of 3302 days or 9.0 years before diagnosis (SD 1.1, min 6.8, max 10.7)." (PMID 33903674, 2021). "In this mutation sequence, the BAP1 mutation has been assumed to occur relatively late in tumor progression, preceded by oncogenic mutations in G-protein subunits including GNA11 and GNAQ that are present in as high as 83–96% of UM7." (PMID 33903674, 2021). "We gained some insight into its function by comparing transcriptome abundances between BAP1 mutation/deletion and BAP1 wild type tumours, where we found replicated up-regulation of the RET proto-oncogene." (PMID 34580349, 2021).
tumor (continued). "Using the same doubling time for the cell population with loss of BAP1 expression, the first tumor cell with lost BAP1 expression appeared 3302 to 3328 days before diagnosis, when the tumor was 166 to 192 days or about 0.5 years old." (PMID 33903674, 2021). "It is important to note the role of tumor architecture and vascular framework, apart from the BAP1 mutation, in the promotion of metastasis in UM." (PMID 33903674, 2021). "BAP1 is one of many genes that undergo mutations to confer increased epithelial to mesenchymal transition of the tumor." (PMID 33903674, 2021). "Our study suggests that a BAP1 mutation occurs early in tumorigenesis, possibly when the tumor consists of a few malignant cells." (PMID 33903674, 2021). "In contrast to using the day of diagnosis as starting point for survival analysis, we added the estimated time that had elapsed from tumor initiation and BAP1 mutation before diagnosis." (PMID 33903674, 2021). "MLL3 mutation in cells results in the defect of BRCA1-associated protein 1 (BAP1) recruitment to enhancers of tumor-suppressor genes, which represses enhancer activity and promotes tumorigenesis." (PMID 34409068, 2021). "It has been documented that BAP1 mutations can downregulate the expression of genes responsible for immune checkpoints and increase inflammation in the tumor microenvironment." (PMID 33903674, 2021). "Lastly, we examined patient survival with the concepts metastasis-free survival after tumor initiation and metastasis-free survival after BAP1 mutation." (PMID 33903674, 2021). "BAP1 (BRCA1-associated protein 1) gene, located on chromosome 3p21, is a tumor suppressor gene that encodes a deubiquitination enzyme regulating several key cellular pathways." (PMID 35052351, 2021). "BAP-1 is one of several genes that undergo mutations to promote epithelial to mesenchymal transition of the tumor cells." (PMID 33800007, 2021). "Using observations of the time elapsed between mitoses, the BAP1 mutation was calculated to occur when the primary tumor had a size of a few malignant cells to 6 mm3, 0.5 to 4.6 years after tumor initiation and at least 9 years before diagnosis." (PMID 33903674, 2021). "Five tumours had BAP1 mutations and copy-neutral LOH, suggesting that the mutations occurred before WGD in the two tetraploid UMs and before the LOH event in the three diploid UMs." (PMID 32415113, 2020). "BAP1-mutated tumours are strongly associated with metastases and have a high melanoma-specific mortality." (PMID 32998469, 2020). "The BAP1 germline mutations are generally deletions or loss-of-function mutations, thus BAP1 was defined as a tumor suppressor gene." (PMID 32028647, 2020). "In further linking BAP1-mediated H2A deubiquitination and tumor suppression, it was found that loss of BAP1 results in the repression or activation of genes that regulate cell death." (PMID 33230107, 2020). "BAP1 is a deubiquitinating enzyme and considered to be a tumor suppressor, and the loss of BAP1 contributes to the metastasis and poor prognosis in various cancers." (PMID 33117084, 2020). "This study found that 97.5% of missense variant carriers developed a BAP1-associated tumor, of which ~12% were RCC." (PMID 32197306, 2020). "We observed that especially high-risk UM tumours (monosomy 3, gain of 8q, loss of BAP1) expressed several HDACs, and showed a high HLA Class I expression." (PMID 33316946, 2020). "The relationships between risk score and previously established prognostic markers, such as tumor stage, chromosome 3 status, mutated BAP1 and molecular subtype, were explored." (PMID 33100273, 2020). "For instance, among the UCHs or ubiquitin carboxy-terminal hydrolases, a subfamily member of DUBs, BAP1 (BRCA1-associated protein 1) possesses unique ability as a tumor suppressor, while others (UCH-L1, UCH-L3, UCH-L5) are characterized as tumor promoters." (PMID 32486284, 2020).
tumor (continued). "Several therapeutic approaches have been explored for BAP1-deficient tumours, including chemotherapeutic drugs (e.g. gemcitabine), radiotherapy and small molecule inhibitors (e.g. EZH2 inhibitors) with limited success." (PMID 33240524, 2020). "Concurrently, we identified a somatic frameshift BAP1 variant, and as expected, immunostaining validated the loss of BAP1 protein in patient-derived tumor specimens." (PMID 32218990, 2020). "The only mutation that occurred more frequently in the HIF1A loss subgroup than the unaltered subgroup was BAP1, which was detected in 9% of all ccRCC tumours." (PMID 32807776, 2020). "In terms of cancer metabolism, the tumor suppressor BRCA1-associated protein-1 (BAP1) inhibits SLC7A11 expression in a de-ubiquitin-dependent manner, resulting in lipid peroxidation and ferroptosis." (PMID 33330074, 2020). "We studied the mRNA expression of HDACs in a panel of 64 primary UMs, and compared their expression with the tumour’s chromosome 3, chromosome 8q and BAP1 status, which are indicators of a high risk of metastases formation." (PMID 33316946, 2020). "Among the latest advances towards better understanding of this tumour, the discovery of BAP1 gene mutations in MMe cells is one of the most intriguing due to potential translational implications." (PMID 30669483, 2019). "When analysing all cases, gain of chromosome 8q was related to an increased MVD (p = 0.029), but most tumours with gain of 8q also demonstrated BAP1 loss." (PMID 31337000, 2019). "Within the group of disomy 3 tumours (n = 22), BAP1 loss (n = 6) was still related to a higher MVD compared to tumours that expressed BAP1 (n = 16, p = 0.008)." (PMID 31337000, 2019). "An immediate implication of this finding concerns the tumor-type-specific spectrum of BAP1 and ASXL mutations." (PMID 30664650, 2019). "By learning from 6800 tumor images, the deep learning model detected features that are strongly associated with nuclear BAP1 expression." (PMID 31623293, 2019). "From this study, we conclude that HIF1a is strongly related to tumour genetics in UM, especially to loss of BAP1 expression, and less to tumour size." (PMID 31323773, 2019). "A clinical trial of a PARP inhibitor (Niraparib) in BAP1-deficient neoplasms including UM is ongoing (NCT03207347)." (PMID 31330784, 2019). "Tumours with monosomy 3/BAP1-loss showed a higher MVD compared to tumours with disomy 3/normal BAP1 expression (p = 0.008 and p = 0.004, respectively)." (PMID 31337000, 2019). "In detail, mutations in two distinct genes were associated with radiomic features: in the BAP1 gene, associated with ill-defined tumor margins and with the presence of calcification, and in the MUC4 gene, associated with exophytic growth." (PMID 31795520, 2019). "The mutation of the remaining allele of PBRM1 or BAP1 would lead to tumorigenesis, and depending on which gene is mutated, to different tumor aggressiveness." (PMID 31861590, 2019). "In particular, BAP1 mutation was detected in the primary tumour and only in one of the three liver lesions, whereas SMAD4 mutation was detected exclusively in one metastatic lesion but not in the primary tumour." (PMID 30306561, 2019). "In the TCGA data, it was confirmed that BAP1 loss relates to increased HIF1a expression within M3 tumours." (PMID 31323773, 2019). "The situation is similar in RCC—a tumour that depends highly on VHL—where BAP1 loss was associated with an increased risk of RCC-related death, although the mechanism is also not yet understood." (PMID 31323773, 2019). "With regard to chromosome status, the sHLA-positive eyes were significantly more often M3 tumours, with a gain of 8q, and loss of BAP1 protein expression." (PMID 31426578, 2019). "A strong association between BAP1 up regulation, adverse tumor phenotype and clinical outcome was found in our cohort of more than 15.800 patients." (PMID 31903168, 2019).
tumor (continued). "Genetic predictors for metastatic tumour behaviour are monosomy 3, gain of chromosome 8q, loss of BRCA1-associated protein 1 (BAP1) expression and a Class II gene expression profile." (PMID 31323773, 2019). "While loss of BAP1 (or M3) is considered a late event during UM tumour evolution, gain of 8q is considered an early event." (PMID 31323773, 2019). "We confirm that within the group of BAP1-expressing tumours from Leiden, gain of 8q was associated with a higher mRNA expression of CD3 (lymphocytes, p = 0.026) and especially of more CD68 (macrophages, p = 0.007)." (PMID 31337000, 2019). "The apparent ability of BAP1 mutations, both somatic and germline variants, to cause multiple tumor types suggests that this gene has a major role in influencing cancer cell growth." (PMID 31635116, 2019). "We identified that BAP1 loss is strongly associated with the expression of HIF1a, even after adjustment for tumour size or chromosome 3 status." (PMID 31323773, 2019). "Epigenetic regulators such as PBRM1 and BAP1 – which act as tumor suppressors – are frequently mutated and associated with distinct clinical outcomes in ccRCC patients." (PMID 30814637, 2019). "Vishva Dixit (San Francisco, USA), who was awarded the CDD Juerg Tschopp Prize 2018, discussed a more recently identified cancer predisposing gene, the BAP1 tumor suppressor." (PMID 31641107, 2019). "Its inhibitory effect on tumor growth can be relieved by the loss of PBRM1, KDM5C, SETD2 or BAP1 to promote robust tumor growth." (PMID 30355451, 2018). "Results identified two known mutations in the tumor biospecimen: BAP1 splice site 1729 + 1 G > A and PBRM1 N258fs*6." (PMID 29440675, 2018). "In order to further examine the impact of BAP1 on ISGF3 expression and activity, we expressed GFP, wild type BAP1, or BAP1 with tumor-derived mutations (N78S or G185R) in BAP1 null ccRCC cell lines UMRC2 and UMRC6." (PMID 30355451, 2018). "Several key genetic alterations are associated with the development and progression of MM including mutations of the CDKN2A/ARF, NF2, and BAP1 tumor-suppressor genes." (PMID 29565815, 2018). "Our data indicate the BAP1-TRAIL association extends beyond MM to other tumours with loss of BAP1 function." (PMID 29345617, 2018). "A second and related subtype comprised “BAP1 driven” cases characterized by tumor clones with BAP1 as a lone mutational driver in addition to VHL." (PMID 29656894, 2018). "The BAP1 gene maps to chromosome 3p21 and is a tumor suppressor gene that encodes a deubiquitinating enzyme (DUB)." (PMID 29946532, 2018). "Our findings also have implications for death receptor agonists as a therapy for BAP1-wild-type tumours as delineation of the underlying mechanism would offer a novel avenue by which to sensitise these tumours." (PMID 29345617, 2018). "A retrospective, validated analysis found that tumours with BAP1 mutations conferred a worse prognosis, higher grade, and worse overall survival when compared to those with PBRM1 mutations or when compared to those without BAP1 mutations." (PMID 30099580, 2018). "Second, genetic testing of the tumor cells from subject 1 identified two mutations specific to the studied tumor: BAP1 splice site 1729 + 1 G > A and PBRM1 N258fs*6." (PMID 29440675, 2018). "To understand common missense variants, we mapped mutations in the human Calypso ortholog, BAP1, from all tumour samples available in cBioPortal25,26, onto the Calypso–ASX structure." (PMID 30258054, 2018). "Ferroptosis appears to be relevant to BAP1 tumor suppressor function and BAP1 mutations that target its catalytic site are defective in regulating SLC7A11 expression and are unable to promote ferroptosis." (PMID 30455474, 2018). "As with VHL, PBRM1 and SETD2, biallelic inactivation of BAP1 via mutation and loss of heterozygosity fit a two-hit tumor suppressor profile." (PMID 30355451, 2018).
tumor (continued). "BAP1 is a histone deubiquitinase that acts as a tumor and metastasis suppressor associated with disease progression in human cancer." (PMID 30400891, 2018). "In tumor K448, we observed 5 distinct BAP1 mutations and 3 SETD2 mutations, but BAP1 and SETD2 mutations never co-occurred within the same clone." (PMID 29656894, 2018). "Within the last decade, the BRCA1-Associated-Protein 1 (BAP1) has been increasingly appreciated for its tumor suppressor activities, given that a loss of BAP1 can drive carcinogenesis in diverse tissue types." (PMID 29166932, 2017). "Mutation in BAP1 leads to defects in the HR DNA repair pathway, and it is considered a tumor suppressor." (PMID 28756516, 2017). "Monosomy 3 affects prognosis due to tumor haploinsufficiency of BAP1—an important BRCA1-associated tumor suppressor gene." (PMID 29326884, 2017). "During the last few years, BAP1 has gained a clinical interest as a critical tumor suppressor as its loss leads to induction of many cancers including lung cancer, breast cancer, uveal melanoma, meningioma, pleural mesothelioma, and renal cell carcinoma." (PMID 28935764, 2017). "We also performed an evaluation of cancer incidence in BAP1 variant carriers and their families, and estimated the degree to which the histopathological features of primary tumours predict germline BAP1 variant status." (PMID 28062663, 2017). "The most aggressive subtype expressing stemness genes has frequent BAP1 mutations, implying its pivotal role in the aggressive tumor progression." (PMID 29018224, 2017). "BAP1 loss was reported to correlate with high Fuhrman nuclear grade, higher tumor stage, and worst overall survival." (PMID 28212566, 2017). "The tumor suppressor BAP1 associates with ASXL1/2 to form the core Polycomb complex PR-DUB, which catalyzes the removal of mono-ubiquitin from several substrates including histone H2A." (PMID 29069806, 2017). "Here we present the case of a 49-year-old female who presented with an asymptomatic dome-shaped pink papule on the dorsal foot which was found on biopsy to be deficient in the BAP1 tumor suppressor." (PMID 29166932, 2017). "In the skin, various neoplasms deficient in BAP1 have been described, typically presenting as dome-shaped to pedunculated growths which range from pink to light brown in color." (PMID 29166932, 2017). "The two patients that were discordant demonstrated loss of BAP1 during progression to metastatic ccRCC, which suggests the presence of a clone in the primary tumor that had lost BAP1." (PMID 28327121, 2017). "Herein, we observed minimal intra- and inter-tumor heterogeneity of BAP1 and PBRM1 loss of expression in metastatic ccRCC tumors." (PMID 28327121, 2017). "Tumor suppressive effects resulting from BAP1 mutations likely involve additional genetic changes such as deletions of chromosome 3p." (PMID 28122578, 2017). "Loss of BAP1 expression has been identified as an adverse prognostic indicator in a number of different cancers, potentially related to its role in tumour suppression." (PMID 29085180, 2017). "BRCA1 associated protein-1 (BAP1) is a novel tumor suppressor that has recently been shown to be somatically mutated in several cancers." (PMID 29088836, 2017). "The fact that in UMs these SF3B1 mutations are almost mutually exclusive with BAP1 mutations suggests different pathways in the oncogenesis and/or malignant progression of these neoplasms." (PMID 26769193, 2016). "Germ-line loss of BAP1 leads to a predisposition for cancer and BAP1 tumours are associated with high tumor aggressiveness and poor prognosis." (PMID 26739236, 2016). "A concomitant GNA11 mutation was present in this tumor while immunohistochemistry showed intact nuclear BAP1 expression." (PMID 26769193, 2016). "We reported a novel 4-base insert somatic mutation in BAP1 in a MM patient’s tumor sequencing results." (PMID 27187383, 2016).